TERT (telomerase reverse transcriptase)
Diseases named in the same sentence as TERT in open-access papers (continued):
Sharing a sentence is not in itself a finding about the gene and the disease.
melanoma (continued). "Other somatic mutations have also since been identified in melanomas including TERT, NRAS, NF1, and KIT in approximately 70-85%, 20-30%, 10-15, and 10% of melanomas, respectively." (PMID 37841001, 2023). "Hence, it is not clear whether TERT promoter mutations are associated with resistance to targeted therapy in melanoma." (PMID 37296851, 2023). "There is evidence for a baseline TERT-specific CD4+ T cell immune response, occurring in over 50% of melanoma patients, rising to 80% in ICI responders." (PMID 37418389, 2023). "When analysing 500 bp upstream regions using melanoma WGS data, we found that the TERT promoter stood out as highly significant (q = 1.3 × 10−6), and that TTCCG-related hotspot mutations were markedly absent among the top results using our approach." (PMID 36396655, 2022). "Recently, it was reported that interaction of PITX1 and ZCCHC10 contributes to TERT regulation in melanoma cells, and it was shown that PITX1 binds to the TERT promoter in gastric cancer cells." (PMID 35267575, 2022). "In this proof of principle study we developed a pilot melanoma NGS panel for ctDNA analysis incorporating 15 genes and the TERT promoter." (PMID 35494035, 2022). "A total of 6 of 70 melanomas (9%) had TERT rearrangement as assessed by FISH, and 14 of 70 melanomas (20%) were wild type." (PMID 36011010, 2022). "Moreover, mutations of the TERT promoter are more frequent in fast-growing melanomas rather than slow-growing ones and this characteristic could be used to identify more aggressive tumors that might benefit from adjuvant therapy." (PMID 32850962, 2020). "The treatment of melanoma cells with BRAF inhibitors reduced TERT expression and telomerase activity, suggesting that the MAPK pathway was necessary for TERT expression in these cells." (PMID 33024276, 2020). "Given that our MPRA assay was conducted in melanoma cells, it may be possible that such variants, for example, may only be functioning in the context of oncogenic signaling (e.g., oncogenic BRAF), tumor suppressor loss (e.g., CDKN2A), or immortalizing events (e.g., mutation of the TERT promoter)." (PMID 32483191, 2020). "Mutations in the promoter region of the telomerase reverse transcriptase gene (TERTprom) lead to increased TERT expression and telomerase activity and are frequent in BRAFV600 mutant melanoma." (PMID 32290374, 2020). "With the recent emergence of next-generation-sequencing (NGS) analyses, concomitant somatic genomic alterations have been identified in samples of BRAF mutant melanomas, such as CDKN2A, PTEN, RAC1, and TERT promoter." (PMID 32784823, 2020). "Many of the SV events targeted well-known melanoma driver genes (CDKN2A, NF1, PTEN, and TERT), exemplifying their role in mucosal melanoma pathogenesis." (PMID 31320640, 2019). "DMs also tend to have lower DNA copy number alterations than other melanoma subtypes; the few focal deletions that have been observed target CDKN2A and NF1, whereas amplifications affect EGFR, CDK4, MDM2, TERT, MAP3K1, MET, YAP1 and NFKBIE13." (PMID 30511391, 2019). "Ectopic expression of wild-type (WT) TERT, or either of the two catalytically impaired TERT mutants, FVYL1016 or FVYL1028, partially protected melanoma cells from cell death induced by NRAS depletion." (PMID 29695835, 2018). "In summary, our study suggests that TERT is upregulated through various genetic and epigenetic alterations in AYA melanoma." (PMID 28378855, 2017). "To determine the effect of ZNF148 depletion on expression of TERT and CLPTM1L in pancreatic, lung, testicular, and melanoma cell lines (n=8 total), we used siRNA-mediated PTGS." (PMID 28447668, 2017). "The three siRNAs altered TERT expression in four additional cancer cell lines from pancreas (MIA PaCa-2), testis (2102Ep), lung (NCI-H460) and melanoma (UACC1113)." (PMID 28447668, 2017).
melanoma (continued). "To identify the link between MAPK pathway activation and TERT transcription, we investigated the expression of different transcription factors of the ETS family in melanoma cell lines." (PMID 27449293, 2016). "Acral melanomas exhibited differential methylation at the gene bodies of MGMT (4% hypomethylation in acral melanoma group, P = 7e − 3) and TERT (9% hypermethylation in acral melanoma group, P < 1e − 3) compared to nonacral tumors." (PMID 26106605, 2015). "The TERT promoter mutation, while not specific to AFX-like morphology, is a frequent driver mutation in melanoma." (PMID 40125165, 2025). "If the cutoff of positivity is 50%, three-quarters of the melanomas were positive for TERT expression, while one-quarter were negative." (PMID 40361989, 2025). "Only a few studies have been published on TERT immunohistochemistry in melanoma, and none have focused on thin melanomas." (PMID 40361989, 2025). "TERT fusions are gaining attention as potential therapeutic targets, and it was previously reported in the metastasis of a patient with advanced melanoma without immunotherapy." (PMID 40737104, 2025). "There are also differences in subtypes and mutation patterns in paediatric melanoma compared to adult melanoma, such as the relatively higher incidence of Spitzoid melanomas and the relative lack of BRAF V600E and TERT promoter mutations." (PMID 40926920, 2025). "Interestingly, although telomerase reverse transcriptase (TERT) promoter mutations did not independently have a statistically significant effect on the recurrence risk and survival of the patients in our cohort, TERT-promoter mutations were identified in 83 % of the primary melanomas." (PMID 38158497, 2024). "Aside from TERT, the other seven eQTLs are melanoma-specific, and their target genes have not been appreciably recognised as melanoma drivers." (PMID 39367275, 2024). "Thus far, the most characterised non-coding driver is located in the promoter of the telomerase reverse transcriptase (TERT) gene, which upregulates TERT expression in melanoma and many other cancer types." (PMID 39367275, 2024). "As such, along with its crucial role in melanoma resistance, more studies on JNK and TERT promoter in BCC may uncover more information on advanced and treatment-resistant BCC." (PMID 36612301, 2023). "As TERT alterations are common in BRAF V600 mutant melanomas and plays an important role in controlling the apoptosis of cancer cells, combined therapies targeting both BRAF and TERT may potentially improvement the survival of these patients." (PMID 37239381, 2023). "Furthermore, 13% (4 of 30) of melanomas from POT1 carriers and 50% (1 of 2) from TERT carriers were completely spitzoid, and therefore, were classified as spitzoid subtype melanomas." (PMID 36876055, 2023). "Spitzoid morphology was also more prevalent in melanomas from individuals with TERF2IP, ACD, and TERT variants compared to noncarriers (OR = 82.4, 95% CI: 21.3-494.6; P < .001)." (PMID 36876055, 2023). "There was no clear relationship between either melanoma stage or BRAF/NRAS mutation status and the presence of TERT promoter variant T349C." (PMID 35494035, 2022). "One melanoma that lacked any TERT alteration had exceptionally long telomeres, characteristic of ALT-mediated telomere maintenance." (PMID 36011010, 2022). "On the other hand, when TERT promoter mutations are present, regardless of PRKAR1A status, melanomas should be considered." (PMID 34943205, 2021). "Mutations in the TERTprom lead to a 2-fold to 4-fold increase in the transcription of TERT, along with enhanced telomerase activity, and are often found in BRAFV600 and NRAS-mutant melanomas, where the combined alterations cooperate in boosting cancer progression and aggressiveness." (PMID 34123788, 2021).
melanoma (continued). "By examining the recurrently mutated TERT promoter, we found that the DeepMEL2 model did not use ETS motifs to classify melanoma enhancers." (PMID 33832990, 2021). "The frequency of mutations in the genes is consistent with that reported in the literature for IDH1 and IDH2 in brain tumors, EGFR and KRAS in NSCLCs, KRAS and NRAS in CRCs, BRAF, RAS, PIK3CA, and TERT in thyroid nodules, BRAF, NRAS and cKIT in melanoma, and KRAS in pancreatic pre-operative samples." (PMID 32340363, 2020). "If additional mutations are acquired such as TERT promoter mutations on both non-CSD and CSD skin, this results in further proliferation toward melanoma." (PMID 33339193, 2020). "Unlike mutations in the TERT promoter, mutations in the SDHD promoter were found exclusively in melanoma and not in other cancer types." (PMID 33024276, 2020). "A similar proportion of TERT-responders at the baseline was reported in advanced melanoma against the single GV1001 peptide, while no response against this epitope was detected in metastatic NSCLC patients." (PMID 32630460, 2020). "Future in vitro studies should clarify if BRAF/TERT mutant melanoma cell lines, after exposure to MAPKi and to stimuli activating the TNFR superfamily, show different TERT expression and telomerase activity, as well as different telomere length based on TERTprom mutation type." (PMID 32290374, 2020). "Given the difficulty encountered with sequencing of the TERT promoter using NGS, an alternative custom melanoma panel based on ddPCR could be developed." (PMID 32785074, 2020). "As an example in melanoma, T > G at −57 base pairs from the transcription start site (TSS) generates an E-twenty-six (ETS) transcription factor-binding site that leads to the upregulation of TERT transcription." (PMID 32082377, 2019). "To do this, we analyzed BRAF, NRAS and TERT promoter mutant ctDNA using serial blood samples from melanoma patients with and without confirmed disease recurrence." (PMID 30719207, 2019). "Although TERT is one of the most frequently involved genes in human non UV-induced melanomas it has never been found amplified in COMs." (PMID 31921654, 2019). "To rule out this possibility, we treated NRAS-mutant melanoma cells with a cdk4/6 inhibitor to induce cell cycle arrest and assessed TERT levels." (PMID 29695835, 2018). "Oncogenes may also be amplified in melanoma, as is the case of CCDN1, KIT and telomerase reverse transcriptase (TERT)." (PMID 30166456, 2018). "Interestingly, however, at least two of these AYA cases had undetectable or low levels of TERT mRNA and complete loss of p16 expression in our study (ID#3 and ID#15), suggesting that the order of these events during tumor evolution may be different in a subset of AYA melanomas than in adults." (PMID 28378855, 2017). "One mutated case was a superficial spreading melanoma diagnosed in 1999, that did not display BRAF, NRAS and TERT promoter mutations, and the patient was alive at the last follow-up (180 months)." (PMID 28662141, 2017). "There was no trend for nucleolar expression (p=0.41), but a statistically highly significant positive trend for non-nucleolar TERT detection with melanoma progression (p=0.006)." (PMID 29262649, 2017). "We found that only non-nucleolar TERT increased significantly in prevalence with melanoma progression." (PMID 29262649, 2017). "Dysplastic nevi were estimated to transform very rarely into melanoma (∼1 in 30,000), implying that the non-nucleolar TERT seen here in about 40% of dysplastic lesions is not sufficient for immortality." (PMID 29262649, 2017). "TERT immunostaining has not to our knowledge previously been analyzed as nucleolar or non-nucleolar relative to melanoma progression." (PMID 29262649, 2017). "We also report for the first time a pathologically significant aspect of TERT localization relative to the nucleolus: only non-nucleolar TERT increases in prevalence with melanoma progression." (PMID 29262649, 2017).
melanoma (continued). "The negative impact of genetic and epigenetic alterations of TERT were also confirmed in a population of adolescent and young patients with melanoma." (PMID 29156643, 2017). "Our study suggests that TERT promoter alterations, specifically CpG dinucleotide methylation, may have prognostic value in AYA melanoma." (PMID 28378855, 2017). "We first showed that normal human epidermal melanocytes (NHEM) did not express TERT; whereas, melanoma cell lines expressed different levels of TERT." (PMID 27449293, 2016). "In further support, the melanoma SP shows upregulated expression of factors that by others have been assigned to (candidate) melanoma CSC, including ABCB1, DNMT3B, EPAS1, JARID1B and TERT." (PMID 24098529, 2013). "Depending of ratio between the full-length TERT and spliced TERTisoforms, melanoma cells were characterized as positive and negative for telomeraseactivity." (PMID 20157588, 2008). "Despite the absence of additional MAPK mutations, melanomas with Class II and III MAP2K1 mutations progressed to metastasis in one-eighth and one-third of cases, respectively, with the presence of TERT-p mutations being an independent predictor for metastatic disease." (PMID 40107205, 2025). "In BRAFV600E-driven human cancer cells, including melanoma cell line A375, thyroid cancer cell lines BCPAP and 8305 C, and breast cancer cell line MDA-MB-231, MAPK/ERK signaling affects the binding capacity of GABP to mutant TERT promoter and eventually results in TERT activation." (PMID 38278800, 2024). "Interestingly, in the 57,490,258–58,411,259 pb region of chromosome 21 associated with two traits (VM and VN), we found five candidate genes (LPCAT1, CLPTM1L, TERT, TRIP13, and BRD9), all of which were related to the main types of skin cancer, i.e., melanoma and cutaneous squamous cell carcinoma." (PMID 39199954, 2024). "Telomerase reverse transcriptase (TERT) aberrations are the most common noncoding mutation (i.e., mutation of regions of DNA that do not code for amino acids) in melanoma expressed in early melanoma progression following MAPK pathway activation." (PMID 37239381, 2023). "Compared to noncarriers (n = 139 melanomas), POT1 carriers (OR = 225.1, 95% confidence interval: 51.7-980.5; P < .001) and individuals with TERF2IP, ACD, and TERT variants (OR = 82.4, 95% confidence interval: 21.3-494.6; P < .001) had increased odds of spitzoid morphology." (PMID 36876055, 2023). "We identified TERT expression in melanoma as a new biomarker as well as a novel therapeutic target, which not only could cooperate with inhibitors of the MAPK pathway but also treat melanoma resistant to inhibitors of MAPK pathway." (PMID 37296851, 2023). "Although NGS may have utility in identifying additional driver mutations, such as TERT promotor mutations, which may help in differentiating atypical DPN from DPN-like melanoma, this molecular technique may not be available at all centers." (PMID 35336833, 2022). "In contrast, PEM typically bear no mutations in TERT promoter or unbalanced copy number changes in known oncogenes (RREB1, MYB1, CCND1, CKND2A) and presence of these molecular changes should raise the suspicion for melanomas." (PMID 34943205, 2021). "Additionally, 31 (52%) UVR-exposed melanomas had TERT and/or TERT promoter mutations, but only one (8%) non-UVR-exposed melanoma had a mutation in this gene." (PMID 33431815, 2021). "Finally, there is no direct evidence that TERT promoter aberrations have a key role in melanoma progression, but this genotyping needs to be confirmed in future research." (PMID 32784823, 2020). "Here, we hypothesized that resistance to TERT inhibition depends on the activation of an adaptive response, which can be exploited for drug combination strategies providing novel avenues to combat NRAS-driven melanoma." (PMID 29695835, 2018). "However the “melanoma-like” non-nucleolar TERT was also found in 20% of benign nevi, and 40% of dysplastic nevi." (PMID 29262649, 2017).
melanoma (continued). "Nucleolar TERT expression did not alter with melanoma progression." (PMID 29262649, 2017). "Additionally, the limited gene panel did not include emerging melanoma drivers, such as TERT or NF1, which could improve detection and stratification in future studies." (PMID 40652269, 2025). "However, TERT activation alone is not enough to maintain the telomere length in melanoma cells." (PMID 37174106, 2023). "Notably, TERT mutant patients may benefit from anti‐CTLA4 treatment, especially for melanoma." (PMID 32810393, 2020). "Therefore, TERT mutant patients may benefit from anti‐CTLA4 treatment, especially for melanoma." (PMID 32810393, 2020). "Among other established melanoma‐related genes that were included in our 360 gene panel and found negative in all index individuals were BAP1, TERT, and MITF." (PMID 40072281, 2025). "We reported increasing nucleolin expression with melanoma progression, which does not readily explain the trend for TERT; however we know of no data on PINX1 expression in melanoma." (PMID 29262649, 2017). "We also detected DNA methylation differences between acral and nonacral melanoma subtypes at MGMT and TERT bodies." (PMID 26106605, 2015). "In tumors, five genes (KIT, MGMT, MITF, TERT, and TNF) exhibited methylation levels significantly different between tumor groups including acral compared to nonacral melanomas and matched primary lesions and metastases." (PMID 26106605, 2015). "AdRGD adenoviruses containing the HSVtk suicide gene under the transcriptional control of the tumor-specific promoter TERT or melanoma-specific promoter Tyrex2, instead of the standard nonspecific CMV promoter, turned out to be promising for melanoma therapy." (PMID 22649681, 2011). "Together, these data support the premise that TERT depletion may lead to both telomeric and non-telomeric DNA damage in NRAS-mutant melanoma cells." (PMID 29695835, 2018). "These combined data indicate that TERT contributes to the survival of NRAS-mutant melanoma and raises the possibility that, in addition to its catalytic role, TERT might also possess a non-catalytic survival role in melanoma." (PMID 29695835, 2018).